WHAMM (WASP homolog associated with actin, golgi membranes and microtubules)
Description:
Acts as a nucleation-promoting factor (NPF) that stimulates Arp2/3-mediated actin polymerization both at the Golgi apparatus and along tubular membranes. Its activity in membrane tubulation requires F-actin and interaction with microtubules. Proposed to use coordinated actin-nucleating and microtubule-binding activities of distinct WHAMM molecules to drive membrane tubule elongation; when MT-bound can recruit and remodel membrane vesicles but is prevented to activate the Arp2/3 complex. Involved as a regulator of Golgi positioning and morphology. Participates in vesicle transport between the reticulum endoplasmic and the Golgi complex. Required for RhoD-dependent actin reorganization such as in cell adhesion and cell migration.
Synonyms: KIAA1971; WHDC1; WHAMM1
Tractability: PROTAC: ubiquitination databases record sites on it.
Gene: Protein-coding gene on chromosome 15 (82,809,599 to 82,836,108, forward strand). Ensembl gene ENSG00000156232.
Subcellular location: Cytoplasm; Endoplasmic reticulum-Golgi intermediate compartment; Cytoplasmic vesicle membrane; Golgi apparatus, cis-Golgi network
Subcellular location (Human Protein Atlas): Cytosol
Pathways (Reactome):
Signal Transduction: RHOD GTPase cycle
Gene Ontology:
Molecular function: Arp2/3 complex binding; microtubule binding; small GTPase binding; actin binding
Biological process: actin filament organization; endoplasmic reticulum to Golgi vesicle-mediated transport; focal adhesion assembly; lamellipodium assembly; plasma membrane tubulation; positive regulation of actin nucleation; Arp2/3 complex-mediated actin nucleation
Cellular component: cytoplasm; cytoplasmic vesicle membrane; cytosol; endoplasmic reticulum-Golgi intermediate compartment; endoplasmic reticulum-Golgi intermediate compartment membrane; Golgi membrane; Golgi apparatus
Genetic constraint (gnomAD): Loss-of-function variants: 45 observed, 47.28 expected, observed/expected ratio (o/e) 0.95, 90% interval 0.75 to 1.22. The upper end of that interval is the gene's LOEUF score, 1.22, which puts it in group 5 of 6, group 1 being the genes least tolerant of losing a copy. Missense variants: 729 observed, 674.66 expected, observed/expected ratio (o/e) 1.08, 90% interval 1.02 to 1.15. Synonymous variants: 253 observed, 240.59 expected, observed/expected ratio (o/e) 1.05, 90% interval 0.95 to 1.17.
Homologues: Orthologues: chimpanzee WHAMM (99% identical), macaque WHAMM (95% identical), dog WHAMM (74% identical), pig WHAMM (74% identical), mouse Whamm (66% identical), rat Whamm (58% identical), rabbit WHAMM (52% identical), tropical clawed frog whamm (48% identical). Paralogues in human: JMY (39% identical), PRR11 (9% identical).
Diseases named in the same sentence as WHAMM in open-access papers:
WHAMM is named in the same sentence as 8 diseases in open-access papers, as found by Europe PMC text mining. Sharing a sentence is not in itself a finding about the gene and the disease. The quoted sentences say what the papers report.
chronic periodontitis (3 papers, 2015 to 2022). A chronic inflammatory process that affects the tissues that surround and support the teeth. "In this study, we conducted a two-stage comprehensive evaluation of the genetic susceptibility of FBXO38, AP3B2 and WHAMM with the diagnosis of severe chronic periodontitis." (PMID 26643602, 2015). "Genome-wide association studies showed the relationship of NIN, ABHD12B, WHAMM, AP3B2, and SIGLEC5 with chronic periodontitis." (PMID 36360171, 2022). "Since the underlying molecular mechanisms of periodontitis are still unclear, the effects of the NIN, ABHD12B, WHAMM, AP3B2, and SIGLEC5 genes on periodontitis have not been elucidated." (PMID 36360171, 2022).
periodontal disease (1 paper, 2019). "Of these, WHAMM and TMCO6 were identified as likely signals of genomic regulation in periodontal disease, due to a significant association between phenotype-associated methylation and gene expression levels at these genes." (PMID 30760334, 2019). "Both findings suggest that WHAMM and TMCO6 are strong candidates to shed light on epigenetic modifications over the course of periodontal disease." (PMID 30760334, 2019).
cancer (1 paper, 2021). A tumor composed of atypical neoplastic, often pleomorphic cells that invade other tissues. "Similarly, the functions of WHAMM and JMY in autophagy could enable cancer cells to better survive in diverse physiological environments and in response to chemotherapy." (PMID 33872315, 2021).
tumor (1 paper, 2021). "However, our current results describing apoptotic requirements for JMY and WHAMM support the idea that these factors also possess key tumor-suppressive features." (PMID 33872315, 2021).
WHAMM also shares sentences with these, for which no sentence is quoted: Gingival bleeding (1 paper); immunodeficiencies (1); renal disorder (1); Sepsis (1).